ASXL1 (ASXL transcriptional regulator 1)
Description:
Probable Polycomb group (PcG) protein involved in transcriptional regulation mediated by ligand-bound nuclear hormone receptors, such as retinoic acid receptors (RARs) and peroxisome proliferator-activated receptor gamma (PPARG). Acts as a coactivator of RARA and RXRA through association with NCOA1. Acts as a corepressor for PPARG and suppresses its adipocyte differentiation-inducing activity (By similarity). Non-catalytic component of the PR-DUB complex, a complex that specifically mediates deubiquitination of histone H2A monoubiquitinated at 'Lys-119' (H2AK119ub1). Acts as a sensor of N(6)-methyladenine methylation on DNA (6mA): recognizes and binds 6mA DNA, leading to its ubiquitination and degradation by TRIP12, thereby inactivating the PR-DUB complex and regulating Polycomb silencing. The PR-DUB complex is an epigenetic regulator of gene expression and acts as a transcriptional coactivator, affecting genes involved in development, cell communication, signaling, cell proliferation and cell viability. ASXL1, ASXL2 and ASXL3 function redundantly in the PR-DUB complex (By similarity). The ASXL proteins are essential for chromatin recruitment and transcriptional activation of associated genes (By similarity). ASXL1 and ASXL2 are important for BAP1 protein stability. Together with BAP1, negatively regulates epithelial-mesenchymal transition (EMT) of trophoblast stem cells during placental development by regulating genes involved in epithelial cell integrity, cell adhesion and cytoskeletal organization.
Synonyms: KIAA0978; BOPS; MDS
Tractability: PROTAC: UniProt records ubiquitination sites on it; ubiquitination databases record sites on it.
Gene: Protein-coding gene on chromosome 20 (32,358,266 to 32,439,319, forward strand). Ensembl gene ENSG00000171456.
Subcellular location: Nucleus
Subcellular location (Human Protein Atlas): Nucleoli; Nucleoplasm
Pathways (Reactome):
Metabolism of proteins: UCH proteinases
Gene Ontology:
Molecular function: protein binding; chromatin binding; nuclear retinoic acid receptor binding; peroxisome proliferator activated receptor binding; transcription coactivator activity; DNA binding
Biological process: animal organ morphogenesis; negative regulation of fat cell differentiation; negative regulation of peroxisome proliferator activated receptor signaling pathway; positive regulation of retinoic acid receptor signaling pathway; positive regulation of transcription by RNA polymerase II; response to retinoic acid; regulation of DNA-templated transcription
Cellular component: PR-DUB complex; nucleoplasm; nucleus
Genetic constraint (gnomAD): Loss-of-function variants: 64 observed, 85.85 expected, observed/expected ratio (o/e) 0.75, 90% interval 0.61 to 0.92. The upper end of that interval is the gene's LOEUF score, 0.92, which puts it in group 3 of 6, group 1 being the genes least tolerant of losing a copy. Missense variants: 1,785 observed, 2,022.9 expected, observed/expected ratio (o/e) 0.88, 90% interval 0.85 to 0.92. Synonymous variants: 739 observed, 778.14 expected, observed/expected ratio (o/e) 0.95, 90% interval 0.89 to 1.01.
Gene-disease validity (ClinGen):
ClinGen rates the evidence that ASXL1 causes each of these diseases.
Bohring-Opitz syndrome (autosomal dominant): Definitive.
Homologues: Orthologues: chimpanzee ASXL1 (98% identical), macaque ASXL1 (95% identical), dog ASXL1 (82% identical), guinea pig ASXL1 (77% identical), pig ASXL1 (77% identical), rabbit ASXL1 (77% identical), mouse Asxl1 (73% identical), rat Asxl1 (72% identical), zebrafish asxl1 (35% identical), tropical clawed frog asxl1 (27% identical), Drosophila melanogaster Asx (16% identical). Paralogues in human: ASXL3 (30% identical), ASXL2 (27% identical).
Diseases named in the same sentence as ASXL1 in open-access papers:
ASXL1 is named in the same sentence as 173 diseases in open-access papers, as found by Europe PMC text mining. Sharing a sentence is not in itself a finding about the gene and the disease. The quoted sentences say what the papers report.
myeloid malignancies (115 papers, 2013 to 2026). "They found that p.G646Wfs*12 variants with VAF ≥ 10% were associated with age, and the most frequent ASXL1 mutation was also in CH, as in myeloid malignancies." (PMID 40773119, 2025). "Myeloid malignancies were diagnosed in 3 of 5 patients with ASXL1 variants, 1 of 4 with TET2 variants, and 0 of 3 patients with DNMT3A variants." (PMID 40179146, 2025). "In the absence of these three major driver mutations, screening for other mutations associated with myeloid neoplasms, such as ASXL1, EZH2, TET2, IDH1, IDH2, SRSF2, and SF3B1, can help establish the clonal nature of the disease." (PMID 41514563, 2025). "ETNK1 mutation is an early event in myeloid neoplasms, often co-occurring with ASXL1, TET2, EZH2, RUNX1, and SRSF2 mutations." (PMID 40074445, 2025). "C.1934dupG; p.G646Wfs*12 is the most common ASXL1 mutation both in human CH and myeloid malignancies." (PMID 40773119, 2025). "Although CH-associated mutations have primarily been studied in myeloid malignancies, recent studies have reported ASXL1 mutations in T-cell–mediated conditions such as aplastic anemia (AA) and large granular lymphocytic leukemia (LGLL)." (PMID 40773119, 2025). "Among these, ASXL1 mutations were the most frequent co-mutations in our cohort, consistent with their known association with poor prognosis and disease progression in myeloid malignancies." (PMID 40806796, 2025). "Herein we employed genetic and pharmacologic approaches to evaluate the therapeutic potential of targeting KDM6B in ASXL1 mutation–associated myeloid malignancies." (PMID 37917239, 2024). "ASXL1 mutation frequently occurs in all forms of myeloid malignancies and is associated with aggressive disease and poor prognosis." (PMID 37917239, 2024). "In summary, this study demonstrated that co-occurring mutations of Asxl1 and Srsf2 accelerate the development and enhance the severity of myeloid malignancies." (PMID 38017104, 2024). "Mutations in ASXL1, a candidate tumor suppressor gene, are frequently observed in myeloid malignancies, such as acute myeloid leukemia and myelodysplastic syndrome (MDS), which are often associated with a poor prognosis." (PMID 38791157, 2024). "ASXL1 belongs to an oncogene with unstable genome and recent studies have shown that mutations in ASXL1 are found in hematopoietic cells of various myeloid tumors such as myelodysplastic syndrome and chronic myelomonocytic leukemia." (PMID 36631868, 2023). "The NM_015338.6:c.1934dup (rs750318549) variant observed in ASXL1 is a known mutation found in >50% of myeloid malignancies." (PMID 37379307, 2023). "The most commonly observed ASXL1 mutations in myeloid malignancies are heterozygous and give rise to truncated ASXL1." (PMID 36068610, 2022). "It is known that the ASXL1 mutation, which is the most common epigenetic mutation in myelofibrosis, reduces overall survival not only in myelofibrosis but in all myeloid neoplasms." (PMID 35145818, 2022). "The most frequent ASXL1 mutations found in myeloid neoplasms are located at exon 12, with an overall incidence that ranges from <7% of patients with essential thrombocytopenia (ET) or polycythaemia vera (PV), to almost 40% of primary myelofibrosis cases." (PMID 35626091, 2022). "A mechanistic explanation for the mutual exclusivity of ASXL1 mutations with ASXL2 mutations in myeloid malignancies remains to be clarified." (PMID 36068610, 2022). "ASXL1 mutations are also commonly detected in other myeloid malignancies and are generally associated with a poor clinical outcome." (PMID 35902731, 2022). "Recurrent ASXL1 mutations have been reported in a variety of myeloid neoplasms and have been linked to an aggressive disease course, blast transformation, and poor clinical outcome." (PMID 34884997, 2021). "For instance, ASXL1 mutations are independently associated with a poor outcome in the spectrum of myeloid neoplasms, including a shorter OS and a higher risk of AML progression." (PMID 33925681, 2021).
myeloid malignancies (continued). "Mutations in ASXL1 are frequently found in a variety of myeloid neoplasms, such as MDS, AML, MPNs, and CMML, as well as age-related clonal hematopoiesis in healthy individuals." (PMID 33799787, 2021). "ASXL1 mutations are common in several myeloid neoplasms as well as MDS and are associated with poor outcome." (PMID 34440317, 2021). "In patients with myeloid malignancies, ASXL1 mutations are usually heterozygous frameshift or nonsense mutations leading to C-terminal truncation." (PMID 33483612, 2021). "STAG2 mutations are almost always accompanied by other driver mutations, such as in RUNX1, SRSF2, and ASXL1, but how cohesin mutations induce myeloid neoplasms in conjunction with other driver mutations remains to be determined." (PMID 33799787, 2021). "Germline BAP1 mutations are found in a spectrum of human malignancies, while ASXL1 mutations recurrently occur in myeloid neoplasm and are associated with poor prognosis." (PMID 32683582, 2021). "ASXL1 is frequently mutated in all forms of myeloid malignancies, as in the case of DNMT3A and TET2, and has a role in balancing HSC self-renewal and differentiation." (PMID 33114351, 2020). "On the other hand, ASXL1 mutations in myeloid neoplasms typically occur near the last exon and result in the expression of C-terminally truncated mutant ASXL1 protein." (PMID 32231866, 2020). "We also detected mutations in ASXL1 gene as typical frameshift/stop-gain variants described in myeloid malignancies." (PMID 33003326, 2020). "Based on these results, it would be possible to establish novel promising therapeutic strategies for myeloid malignancies harboring certain gene mutations such as ASXL1 by blocking interactions between ASXL1 and associating epigenetic regulators." (PMID 31921515, 2020). "Mutations in ASXL1 are frequently found in diverse myeloid malignancies and associated with worse outcome." (PMID 31311566, 2019). "Somatic loss-of-function mutations of the additional sex combs-like transcriptional regulator 1 (ASXL1) gene are common genetic abnormalities in human myeloid malignancies and induce clonal expansion of mutated hematopoietic stem cells (HSCs)." (PMID 31064769, 2019). "ASXL1 mutations have an important role in the pathogenesis of myeloid neoplasms primarily consisting of nonsense, missense and frameshift mutations resulting in a truncated ASXL1 protein that retains the BAP1-binding domain." (PMID 29345617, 2018). "ASXL1 mutations were found, in diverse types of myeloid neoplasms and, in most cases in combination with other gene mutations." (PMID 30222780, 2018). "Somatic or de novo mutations of Additional sex combs-like 1 (ASXL1) frequently occur in patients with myeloid malignancies or Bohring-Opitz syndrome, respectively." (PMID 29423272, 2018). "Our results in vivo, showing ASXL1 mutations with other gene mutations in 94% of myeloid neoplasms assessed, support this notion." (PMID 30222780, 2018). "ASXL1 mutations are frequently identified in a variety of myeloid neoplasms and are associated with poor prognosis, making the development of molecular therapies targeting these mutations an important goal." (PMID 30013160, 2018). "Since the discovery of ASXL1 mutation in myeloid malignancies in 2009, many studies about its pathophysiology have been reported." (PMID 28697759, 2017). "Nonsense and frameshift-inducing mutations giving rise to truncated isoforms of ASXL1 are among the most frequently observed mutations in myeloid malignancies." (PMID 29037253, 2017). "Asxl1 loss leads to the development of myeloid malignancies in mice, which is associated with dysregulation of H3K27me3 (refs 6, 7)." (PMID 28593990, 2017). "Several studies also showed that ASXL1 mutation was a poor prognostic factor in myeloid malignancies." (PMID 28697759, 2017).
myeloid malignancies (continued). "ASXL1 mutations are common in myeloid neoplasms, including myelodysplastic syndrome (MDS), chronic myelomonocytic leukemia (CMML), primary myelofibrosis, and acute myeloid leukemia (AML)." (PMID 28533818, 2017). "In this study, we have corrected a specific point mutation in ASXL1, a gene commonly mutated in myeloid malignancies, in a leukemia cell line using CRISPR/Cas9 technology." (PMID 26623729, 2015). "ASXL1 is frequently mutated in a range of myeloid malignancies, including the myelodysplastic syndromes (MDS), chronic myelomonocytic leukemia (CMML), and acute myeloid leukemia." (PMID 26623729, 2015). "Our dataset contained neutral polymorphisms and mutations associated with myeloid malignancies from epigenetic regulators ASXL1, DNMT3A, EZH2, and TET2." (PMID 24348198, 2013). "For example, Park and Yoshizato showed that the most common mutations in AA patients were BCORL1/BCOR, ASXL1, DNMT3A and TET2, among which AA patients with myeloid tumor-related mutations, such as ASXL1, DNMT3A, RUNX1, showed approximately 40-60% response and overall survival after IST." (PMID 39873798, 2025). "Thus, CH-related ASXL1 mutations are thought to represent early genetic events contributing to the development of various myeloid malignancies." (PMID 40773119, 2025). "ASXL1 mutations in myeloid neoplasms usually cause dysplasia." (PMID 39858009, 2025). "Moreover, some reports proposed the possible association between ASXL1 mutations and male sex, older age (more than 65 years), and lower platelet counts in patients with myeloid malignancies." (PMID 38807730, 2024). "Therapies targeting ASXL1 mutation–mediated epigenetic alterations may improve the survival of patients with ASXL1 mutation–associated myeloid malignancies." (PMID 37917239, 2024). "This preclinical finding provides compelling evidence that targeting KDM6B may be a therapeutic strategy for myeloid malignancies with ASXL1 mutations." (PMID 37917239, 2024). "Standard therapies for myeloid malignancies have limited efficacy when mutated ASXL1 is present." (PMID 37917239, 2024). "This study provides solid preclinical evidence that KDM6B may serve as a therapeutic target for patients with ASXL1 mutation–associated myeloid malignancies." (PMID 37917239, 2024). "Importantly, our study provides scientific evidence for the therapeutic potential of targeting KDM6B in treating ASXL1 mutation–associated myeloid malignancies." (PMID 37917239, 2024). "Finally, what is the mechanistic explanation for the mutual exclusivity of ASXL1 mutations with ASXL2 mutations in myeloid malignancies, and why are ASXL1 mutations more prevalent in myeloid malignancies compared with ASXL2 mutations?" (PMID 36068610, 2022). "Patients with myeloid malignancies that harbor ASXL1 mutations may be selectively sensitive to BET inhibitors." (PMID 36077629, 2022). "Similarly to other myeloid neoplasms, ASXL1 mutations have been also (recurrently) associated with a worse prognosis in SM." (PMID 35626091, 2022). "ASXL1: Several studies showed that ASXL1 somatic mutations are among the most frequent variants in all subtypes of myeloid malignancies including MDS (11–21% cases), AML (5–11%), myeloproliferative neoplasm (MPN), and chronic myelomonocytic leukemia (CMML) (40–50%)." (PMID 36035165, 2022). "Moreover, recent studies have shown the interaction of RUNX1 with other frequently co-mutated drivers, such as STAG2 and ASXL1, thus promoting the advancement of myeloid neoplasms." (PMID 33799787, 2021). "Patients with multiple myeloid malignancies frequently harbor an ASXL1 mutation." (PMID 33483612, 2021). "In this context, identifying mutations in MPN driver genes (JAK2, CALR, or MPL) or other myeloid neoplasm-associated genes (ASXL1, EZH2, TET2, IDH1, IDH2, SRSF2, and SF3B1) hints to the clonality of hematopoiesis and allows distinction from reactive conditions." (PMID 34830822, 2021).
myeloid malignancies (continued). "Studies using ASXL1-depleted human hematopoietic cells and ASXL1 knockout mice have shown that deletion of wild-type ASXL1 protein leads to impaired hematopoiesis and accelerates myeloid malignancies via loss of interaction with polycomb repressive complex 2 proteins." (PMID 32231866, 2020). "We identified HIF-1α targeting a new pathway which may be critical for the leukemic progression of RUNX1/ASXL1-mutated myeloid malignancies." (PMID 31640815, 2019). "This led us to hypothesize that loss of Asxl1 in BM niche cooperated with Asxl1-deleted HSC/HPCs to contribute the pathogenesis of myeloid malignancies in vivo." (PMID 29423272, 2018). "ASXL1 mutations occur frequently in myeloid neoplasms and are associated with poor prognosis." (PMID 30013160, 2018). "The hematopoietic phenotypes observed in OsxCre;Asxl1fl/fl mice indicate that ASXL1 is required for the maintenance of normal function of the BM niche, and Asxl1 loss in the niche may contribute to the pathogenesis of myeloid malignancies." (PMID 29423272, 2018). "Since selection of the cases was based on the positivity in at least one sample for ASXL1 c.1934dupG mutation and the availability of serial samples from the same patient, we believe this series likely reflects a random selection of myeloid neoplasms with ASXL1 c.1934dupG mutation." (PMID 30222780, 2018). "The polycomb repressive complex 2 (PRC2) silences H3K27 to H3K27me3, and several genes encoding components of the PRC2; EZH2, SUZ12, JARID2 and also mutations in ASXL1 coding for the PRC2 associated protein ASXL1, have been found to be mutated in myeloid malignancies." (PMID 30304859, 2018). "The ASXL1 is frequently mutated in a range of myeloid malignancies." (PMID 28055972, 2017). "Additional sex combs-like 1 (ASXL1) is frequently mutated in myeloid malignancies." (PMID 28697759, 2017). "ASXL1 mutations are found in a spectrum of myeloid malignancies with poor prognosis." (PMID 27352931, 2016). "Moreover, GATA2 and MEIS1 knockdown in the leukemic cell lines K562 and Kasumi-1 reduced the frequency of CFU-Cs, verifying that GATA2 and MEIS1 could be potential therapeutic targets for ASXL1 mutation–associated myeloid malignancies." (PMID 37917239, 2024). "Isolated isochromosome 17q, i(17q), accounts for less than 1% of myeloid neoplasms, including AML, MDS, and myeloproliferative neoplasms (MPN), and frequently harbors mutations in SETBP1, ASXL1, SRSF2, and NRAS." (PMID 41148513, 2026). "Next, we introduce several in vivo models developed by different research groups, which allow for investigating the impact of ASXL1 alteration in hematopoiesis and myeloid malignancies." (PMID 40773119, 2025). "The ASXL1 truncation drives myeloid neoplasms through PRC2-mediated epigenetic dysregulation and confers distinct therapeutic vulnerabilities." (PMID 40772034, 2025). "In conclusion, the majority of myeloid neoplasm-associated gene variants in AA patients affected TET2, ASXL1 and MPL, and epigenetic- and signal transduction pathway-related genes were the most commonly involved." (PMID 41477271, 2025). "NGS is essential for this diagnosis, as it enables detection of at least one somatic mutation in genes commonly mutated in myeloid neoplasms (e.g., DNMT3A, TET2, ASXL1, SF3B1, SRSF2, etc.)." (PMID 41464583, 2025). "Together, these data indicate that inactivation of Asxl1 and Ezh2 in HSPCs results in development of aggressive myeloid malignancies as observed in human patients." (PMID 40561338, 2025). "Our results demonstrated that MDS/MPN is characterized by the presence of mutations commonly identified in myeloid neoplasms, such as TET2, ASXL1, SRSF2, and SF3B1." (PMID 39337700, 2024).